BCL2 (BCL2 apoptosis regulator)
Diseases named in the same sentence as BCL2 in open-access papers (continued):
Sharing a sentence is not in itself a finding about the gene and the disease.
tumor (continued). "lncRNA ANRIL knockdown in tumor cells inhibits proliferation, induces apoptosis and increases cisplatin cytotoxicity in tumor cells via impairment of the drug transporters MRP1 and ABCC2, which can be restored by treatment with human MK in a caspase-3/BCL-2-dependent manner." (PMID 35204785, 2022). "Immunohistochemistry (IHC) showed tumor cells are positive for vimentin, ALK, BCL2, and SMA." (PMID 36304484, 2022). "In the H226 xenograft, tumor growth was suppressed by DCA/Nic and partially mediated by apoptosis (downregulation of Bcl-2 and XIAP), anti-proliferation (decrease in expression of PCNA and Akt), G2/M arrest (CDK7 downregulation) and suppressed migration (decline in expression β-catenin)." (PMID 36304150, 2022). "Interestingly, the tumor suppressor MEG3 promotes tumor progression through targeting miR-4261, modulating the expression of DKK2, β-catenin, Bcl-2, and c-Myc, thus activating the Wnt/β-catenin signaling pathway." (PMID 35448163, 2022). "Using cell lines and patient-derived in vivo xenograft models, we show BCL-2 pathway-mediated apoptosis induction and decelerated tumor cell counts in KMT2A-rearranged B-ALL but not in other cytogenetic subtypes." (PMID 35778418, 2022). "The activities of Bcl-2 and Bcl-XL are important in tumor development, so it was surprising that we did not see an effect with ABT263 in our Apc inflammation–driven models." (PMID 36860494, 2022). "This contrasts with previous findings showing lack of effect of single BH3-mimetic treatment in U87 tumours in vivo, thus emphasising a key role for multiple BCL-2 proteins in enabling GBM survival." (PMID 35473984, 2022). "ABT-737, a Bcl-2 inhibitor, used either as a pre-treatment or synergistically with anti-CD19 CAR T cells derived from healthy donors or from B cell ALL patients, enhanced tumor cell apoptosis." (PMID 35203517, 2022). "Furthermore, we found that Bcl-2 protein expression significantly decreased by 15% and 35% in the RTP-L and RTP-H treatment groups, respectively, compared with the tumor group." (PMID 35269987, 2022). "The primary role of BCL2 overexpression in tumor cells is to expand their resistance to metabolic stress in the tumor microenvironment, independent of cell death signaling." (PMID 36299777, 2022). "Furthermore, immunohistochemistry showed that the expression levels of BCL‐2 and MCL‐1, two major cell apoptosis‐related molecules, were decreased by vandetanib in K562 tumor tissues." (PMID 35689424, 2022). "We also examined the protein level of tumor tissues in two groups, which showed that PHGDH and pathway-related indicators β-catenin, c-myc, cyclin D1, PCNA, Bcl2, N-cadherin, vimentin, and Snail expression level were lower and BAX and E-cadherin higher in CBR-5884 group." (PMID 36105480, 2022). "The results showed that tumor tissues from EGFR TKI-resistant patients had significantly increased GLI1, SMO, BCL2, and SNAIL protein levels compared with those from TKI-sensitive cases, suggesting that these proteins are possibly related to TKI resistance in NSCLC." (PMID 35154464, 2022). "Patients with negative BCL-2 expression were reported to display better disease-free 5-year survival compared to patients with BCL-2 positive tumours." (PMID 35201512, 2022). "BCL2, CDK4 and MCL1 were highly expressed in all tumours studied." (PMID 35249548, 2022). "The lack of significant changes in bcl2 levels herein observed suggests a marginal role of apoptosis in either tumor physiology or larval growth." (PMID 36564370, 2022). "Here, tumor Tregs in vav-BCL-2 mice were not depleted after CPM administration compared to WT mice, leading to a decrease in survival." (PMID 36097618, 2022).
tumor (continued). "In addition, the immunohistochemical results showed the altered staining patterns of BCOR, bcl2, CyclinD1, TLE1, AR, SMA, CD117, STAB2, CD56, and CD99 in tumor tissues after chemotherapy." (PMID 35568949, 2022). "In many cancers, high levels of anti-apoptotic proteins such as Bcl-2, Bcl-xL and Mcl-1 were shown to contribute, not only to lack of response to chemotherapy, but also to tumor initiation and progression." (PMID 35265218, 2022). "Surprisingly, we found that roughly 50% of senescent tumor cells were not expressing Bcl2 at high levels." (PMID 35449130, 2022). "Besides, XIST was reported to act as a miR-449a sponge to modulate the levels of Bcl-2 and cleaved PARP-1 by attenuating the endogenous function of miR-449a, which consequently influenced tumour progression of NSCLC." (PMID 35379783, 2022). "Bcl2, Bax, IL6, TNFα, CASP3, and other potential targets are related, and they may inhibit tumor growth and induce tumor cell apoptosis through AGE/RAGE and other signaling pathways." (PMID 35815259, 2022). "Following combination therapy, the authors observed reduced tumor growth and increased apoptosis along with decreased expression of wild-type FLT3, p65, and NF-κB regulated genes such as cyclin D1 and BCL-2, suggesting the potential use of these inhibitors for treating AML." (PMID 35884618, 2022). "Specifically, PDOs have lower levels of several factors (including B-cell lymphoma 2/Bcl-2, MMP2, Cathepsin D and Survivin) as compared to CTCDOs, suggesting that proteins related to tumor cell survival and aggressiveness increase during sequential stages of the disease." (PMID 35260172, 2022). "BCL-2 inhibitors competitively bind to BCL-2 proteins to release BH3-only proteins and disinhibit BAX/BAK, which eventually initiates the apoptotic cascade of tumor cells." (PMID 35216478, 2022). "Although Bcl-2 has crucial functions in non-cancerous cells, therapies targeting Bcl-2 have a predominant effect on tumor cells." (PMID 35056993, 2022). "When we compared the mutation profiles from diagnosis with those from relapse or progression using paired tumor samples from four patients, truncated or nontruncated mutations were frequently found in CREBBP and BCL2 at the time of diagnosis and relapse." (PMID 36199784, 2022). "For example, in BC, BAG3 up-regulates the expression levels of Bcl-2 and Bcl-xL by targeting HSP70/Mcl-1 signaling pathway and suppresses the chemoresistance of tumor cells, indicating that BAG3 may be a potential target for treating BC." (PMID 36228497, 2022). "RSV treatment applied alone influenced the response of tumor cells in a different way, thus a significant decrease in BCL-2 gene expression in FaDu was recorded without altering the expression in PE/CA-PJ49 cells." (PMID 34204834, 2021). "At the protein level, BCL-2 was detected in normal crypts, however its expression was nearly absent in adjacent tumor tissue, while BCL-XL showed strong positive staining in both normal and tumor tissue." (PMID 34117376, 2021).
tumor (continued). "Moreover, LAF dramatically upregulated the levels of 14-3-3σ in tumour tissues and downregulated the levels of YAP and its regulatory proteins, including BIRC5, c-Myc and Bcl-2." (PMID 34010589, 2021). "In addition, bax, bcl-2, MMP-2, caspase-3 and p-glycoprotein were regulated by CK-M to promote tumor cell apoptosis and inhibit tumor cell invasion, metastasis, and outflow." (PMID 34654430, 2021). "In conclusion, our study suggested that miR-29b-3p could influence DNA damage response by regulating the expression of DNMT3B, Bcl-2, PI3KR1, AKT2, and RBL1, thereby affecting tumor radioresistance." (PMID 34604239, 2021). "Besides, it can promote cell proliferation, invasion, and tumor progression by regulating docetaxel sensitivity and mitochondrial membrane potential, possibly through the AKT/Bcl-2 axis." (PMID 34350290, 2021). "Moreover, IHC assays showed that compared with CRexo, hCRexo treatment significantly increased BCL2, phosphorylated BCL2, PKM2 and GLUT1 expression levels in tumor tissues." (PMID 33456577, 2021). "This indicates that, despite frequent BCL2 upregulation, BCL2 is not a major survival protein for these tumour cells." (PMID 34903710, 2021). "Comparative analysis of BCL-2 gene expression in PE/CA-PJ49 and FaDu cell lines showed that these tumor cells had a similar response to treatment with CisPt and to the combined treatment CisPt + RSV, but they reacted in a different way to treatment with RSV alone (p < 0.03, *)." (PMID 34204834, 2021). "In conclusion, we showed that type I collagen could mediate the tumor progression and chemotherapy though an ITGB1 based manner, which was dependent on BCL9L/β-catenin/BCL2 signaling pathway." (PMID 34319913, 2021). "All CSP components interacted positively with the ABL kinase, ABL1, BCL2, and FLT3 receptors in the tumor cells, and thus may explain a possible mode of action of the extract." (PMID 34451867, 2021). "In accordance with the in vitro data, further detailed analysis of the tumor tissues revealed that the MDR1 and proliferating cell nuclear antigen (PCNA) protein levels were decreased, whereas the γH2AX and apoptosis protein Bcl2 levels were upregulated in the mouse tumors upon Gli2 knockdown." (PMID 35059317, 2021). "The excellent Nur77ΔDBD gene delivery can reverse Bcl-2 from the tumor protector to killer for inhibiting non-pump resistance." (PMID 33924348, 2021). "We also found that B cell related proteins (CD20, BAD, BCL-2, CD27, BIM) were most highly expressed in the stromal compartments while expression of lymphocyte-related markers (CD3, CD8, CD4, Tim-3) were elevated in tumor compartments." (PMID 34838031, 2021). "It will be interesting to investigate whether the combination of Bcl-2 overexpression and other strategies, such as PD-1-CD28 switch and CD40L overexpression, will further improve the anti-tumor effector of CAR-T cells." (PMID 33429845, 2021). "Oblimersen binds to human bcl-2 mRNA-stimulating apoptosis and is believed to facilitate non-apoptotic cell death by autophagy, to inhibit tumor angiogenesis, and to exert immunostimulatory effects." (PMID 34631574, 2021). "In contrast, BCL2GA/AMP is rarely accompanied by BCL2MUT, resulting in high expression of BCL2 protein whose function has not been affected, thus enhancing the anti-apoptotic ability of tumor cells." (PMID 34806851, 2021). "In this study, we found that Bcl-2 siRNA could silence the Bcl-2 gene in B16F10 cells and curb intrinsic tumor resistance to CTND." (PMID 34163720, 2021). "Taken together, this work supports that miR‐140‐3p exerts as a tumor suppressor in CRC progression via targeting BCL9 and BCL2, and suggests miR‐140‐3p‐BCL9/BCL2 axis may be applied in miRNA‐based therapy and prognostication of CRC." (PMID 33838016, 2021).
tumor (continued). "Patients with IDC had high PD-L1 in tumours more frequently than patients with other subtypes (46.7% vs. 16.7%, P = 0.017) and it was also more frequent in B-cell Lymphoma 2 (bcl2) negative patients (58.8% vs. 36.0% in positive patients, P = 0.022)." (PMID 33446741, 2021). "The authors found that this region contains two miR genes, miR-15a and miR-16-1, that both act as tumor suppressors to induce apoptosis by repressing Bcl-2, an anti-apoptotic protein overexpressed in malignant non-dividing B cells and many solid malignancies." (PMID 34831232, 2021). "Our results also indicate that BCL-2 expression is not related to tumor aggressiveness and prognosis after a single surgical treatment." (PMID 33917480, 2021). "In addition, IHC staining of mouse tumour tissues showed that the protein expression of PCNA, Bcl2, vimentin, p-PI3K, and p-AKT was reduced, which was consistent with the results of the in vitro studies." (PMID 33995637, 2021). "In the tumor tissues of SMMC-7721-xenotransplanted BALB/c nude mice, Tf-LP-ERN strongly enhanced the expression levels of Bax, Bad, PUMA, cleaved RARP-1, cleaved caspase-3 and caspase-9, and decreased the expression level of Bcl-2." (PMID 34513705, 2021). "These therapies may target MCL-1 more selectively in tumor cells, and could help circumvent the toxicity expected with direct MCL-1 inhibition in combination with BCL-XL/BCL-2 targeting." (PMID 35008216, 2021). "RSV did not significantly modify BCL-2 gene expression in PE/CA-PJ49 tumor cells, the effect being different from the one induced in HaCaT cells (p < 0.035, *)." (PMID 34204834, 2021). "Finally, we performed HE staining, immunofluorescence staining, immunohistochemical staining, and Western blot analysis on nude mouse tumor tissues to detect protein expression changes in HK2, GLUT1, Ki67, PCNA, CDK2, CyclinD1, Bax, and Bcl-2." (PMID 34893086, 2021). "Western blot and immunohistochemistry assays of tumor tissues showed that SMBJD reduced the ratio of autophagy-related proteins LC3-II/LC3-I, while P62 and apoptosis-related proteins cleaved caspase-3/caspase-3 and Bax/Bcl-2 were upregulated." (PMID 33854428, 2021). "Furthermore, the activation of NF-κB in tumor cells increases their survival due to the increased activity of anti-apoptotic genes including c-FLIP, c-IAP2, Bcl-2, Bcl-xL, and A1." (PMID 33917793, 2021). "Recently, we showed that drugs targeting the BCL-2-regulated apoptosis pathway could kill MPM cell lines in vitro, and control tumor growth in vivo." (PMID 34050131, 2021). "Data analysis yielded five drugs that emerged as potential candidates due to their superior efficacy in tumor cells: paclitaxel, d-actinomycin, volasertib (PLK1 inhibitor), navitoclax (BCL-2/BCL-XL/BCL-w inhibitor) and I-BET-151 (a Bromodomain family inhibitor) (online resource)." (PMID 34417833, 2021). "However, Plonka and colleagues’ contrary findings showed a decrease in Bax to Bcl-2 protein on MCF-7 and T-47D tumour cells treated with Photolon-induced PDT." (PMID 34885994, 2021). "Moreover, the protein expression of cleaved PARP was up-regulated in xenograft tumor tissues in the BBR and regorafenib combined treatment group, while the protein expression of BCL-2 was down-regulated." (PMID 34220494, 2021). "Tumor tissue was defined by cell staining for SSTR2 in the cell membrane and Bcl2 in the cytoplasm." (PMID 33962620, 2021). "We therefore initially examined the expression of Bcl-2-, Bcl-xL and Mcl-1, of which Mcl−1 but not Bcl-2 or Bcl-xL were significantly upregulated in GBM compared with non-tumour tissue." (PMID 34344865, 2021).
tumor (continued). "Moreover, it has been shown that antiapoptotic BCL2 proteins have a role in promoting hedgehog/GLI signaling by enhancing the turnover of a GLI antagonist, SUFU tumor suppressor." (PMID 34282785, 2021). "In this context, >90% of SFT express CD34 and STAT6, while a smaller percentage of tumours may be positive for CD99 (70%), EMA (20%), smooth muscle actin (20%) and BCL-2 (30%)." (PMID 34849218, 2021). "In immunohistochemical analysis, tumor cells were stained for CD34, CD99, and Bcl2." (PMID 33567630, 2021). "This may explain the tumor suppressive function of TRIM16 in GC; as reduction in TRIM16 expression leads to the accumulation of mRNAs from β-catenin, Cyclin D, and BCL2 genes and eventually cancer progression." (PMID 34452557, 2021). "To determine whether BCL-2 upregulation could be identified in patients treated with HER2-targeted therapies, we utilized tumor samples that were previously collected during the TRIO-B-07 clinical trial (NCT#00769470)." (PMID 33951110, 2021). "MiR‐140‐3p served as a tumor suppressor in CRC via targeting BCL9 and BCL2." (PMID 33838016, 2021). "Western blot analysis of tumor tissues showed that irradiation combined with CDC20 inhibition resulted in upregulated pro-apoptosis protein Bax and downregulated anti-apoptosis protein Bcl-2 33-35." (PMID 34512169, 2021). "It was observed that in positive samples all tumor cells stained for ROR1 and BCL2 expression." (PMID 34088900, 2021). "Compared with the control group, the xenograft tumours from mice treated with CVB exhibited an evident decrease in the levels of IGFBP3, p-AKT, p-STAT3, p-ERK, p-JNK, p-P38, Bcl-2, Snail, and Vimentin, while the levels of cleaved Caspase 3 and E-cadherin were increased." (PMID 34512163, 2021). "Compared with chemotherapy alone, Rg3 combined with chemotherapy can not only inhibit tumor neovascularization but also moderately antagonize the generated ones; in addition, it can reduce the expression of VEGF and Bcl-2 and cut down microvessel density of the target tissue." (PMID 34512772, 2021). "In addition, Western blot analysis showed that the expression of pro-apoptosis related proteins in tumor tissues of nude mice in sh-LINC01087#1 group increased markedly, while the Bcl-2 expression decreased dramatically." (PMID 34459789, 2021). "Furthermore, we provided evidence for miR‐140‐3p as a tumor suppressor in CRC progression, regulated cell proliferation, migration, invasion, and apoptosis via targeting BCL9 and BCL2." (PMID 33838016, 2021). "As the differential expression of anti-apoptotic proteins (e.g., MCL-1 or BCL-XL) or pro-apoptotic proteins (e.g., BIM, PUMA, or NOXA) can alter sensitivity to BCL-2 inhibition, we evaluated the expression of BCL2 family transcripts across multiple sarcoma tumor types." (PMID 34065859, 2021). "ABT-737 bound BCL2, BCLxL, and BCLw with high affinity, thereby mimicking the action of BH3-only protein BAD, demonstrating the sub-micromolar killing of primary cancer cells and cancer cell lines as well as anti-tumor activity in mouse models." (PMID 33198338, 2020).